BCL2 (BCL2 apoptosis regulator)
Diseases named in the same sentence as BCL2 in open-access papers (continued):
Sharing a sentence is not in itself a finding about the gene and the disease.
tumor (continued). "Compared with the single delivery of siAPE1 or melatonin, their co-delivery by 125I-loaded PSMA-R12 nanoparticles had superior efficiencies in inhibiting Bcl-2 expression and promoting apoptosis in PCa cells and suppressing PCa tumor growth in vivo." (PMID 39044710, 2024). "In this study, we demonstrated that Paucatalinone A induced tumor cell mitochondria disruption mediated by anti-apoptotic proteins (Bcl-2, Mcl-1), pro-apoptotic family member ERK1/2, or calcium and ROS-triggered mitochondrial permeability transition." (PMID 38590635, 2024). "Meanwhile, the weak fluorescence of Bax (yellow) and strong fluorescence of BCL‐2 (orange) in tumour tissues in the si‐ELFN1‐AS1 combined with the ABT‐263 group were in contrast to those in the other groups." (PMID 38037859, 2024). "Tumor temperature increased to 52 and 57 °C and tumor tissue was strongly eradicated, the expression of Bcl-2 and Ki67 in tumor tissue was significantly decreased." (PMID 39138299, 2024). "The resulting Ch-HAD NPs served as carriers for siRNA targeting the Bcl2 oncogene, aiming to inhibit the oncogene and, consequently, the growth of the tumor." (PMID 39065565, 2024). "In human tumor cells, the Hedgehog (Hh) signaling pathway can prevent cell death by upregulating the antiapoptotic gene Bcl-2." (PMID 39524849, 2024). "COX-2 also promotes the expression of the downstream prostaglandin E2 (PGE2)/Bcl-2 axis; enhances the antiapoptotic ability of tumor cells; and reduces the therapeutic effects of chemotherapy drugs, photodynamic therapy, and radiotherapy." (PMID 38919710, 2024). "Our study depicted that Bcl2 had a strong connection with tumour stroma, notably with suppressor cells originating from myeloid tissues." (PMID 38223131, 2024). "The co-administration of I2 in all doses of Cpp maintained the inhibition of the expression of Survivin and intensified the induction of apoptosis (Bax/Bcl2 index) in concordance with the major reduction in the tumor size." (PMID 39201507, 2024). "Inhibiting BCL-2 activity or reducing BCL-2 protein levels can effectively promote apoptosis in malignant tumor cells and increase sensitivity to radiotherapy and chemotherapy." (PMID 39026380, 2024). "Tumor cells overexpressing BCL-2 or BCL-xL have been found to be more resistant to metabolic stress due to a more efficient coupling of the proton motif force to ATP generation by the F1F0-ATPase." (PMID 40150937, 2024). "Paucatalinone A also decreased the expression of Mcl-1, Bcl-2 and elevated cleaved caspase-3 levels in tumor cells, which were involved in mitochondria-mediated apoptosis." (PMID 38590635, 2024). "ASO drugs targeting BCL2 induced apoptosis in solid tumor cells and increased the sensitivity of tumor cells to chemotherapy." (PMID 38184597, 2024). "Two genes are influenced by miRNA-143, namely programmed death-ligand 1 (B7H1) and the B-cell lymphoma apoptosis regulator (Bcl-2), hence downregulation of miRNA-143 influences tumor B-cell proliferation." (PMID 38828367, 2024). "STAT3 is a signal transducer and transcription activator that dimerized and translocated to the nucleus upon phosphorylation, regulates tumor-related genes (such as Bcl-2 and Snail) involved in cell growth, apoptosis, and migration." (PMID 38182570, 2024). "By inhibiting both Bcl‐2 and Survivin, there is an observed enhancement in radiosensitivity and chemoresistance in tumour cells, ultimately amplifying the therapeutic response against CRC." (PMID 38494866, 2024). "The overexpression of BCL-2 has been shown in AML cells, and aids tumor cell survival and has been associated with resistance to chemotherapy." (PMID 39001536, 2024). "Co-immunoprecipitation analyses showed that both WT Beclin1 and Beclin1 P54A interacted with BCL2, and these bindings were all disrupted in glucose-starved tumor cells." (PMID 38360997, 2024).
tumor (continued). "Co-immunoprecipitation analyses showed that WT Beclin1 and Beclin1 P54A comparably interacted with BCL2 in tumor tissues (Fig. EV5H,I), further supporting that Beclin1 P54 hydroxylation regulates tumor growth in a BCL2-independent manner." (PMID 38360997, 2024). "On the other hand, Bcl-2 plays a tumor suppressor role in the mitochondrial apoptosis pathway by blocking the pro-apoptotic effect of Bax." (PMID 38931473, 2024). "Bcl-2 belongs to the family of pro- and anti-apoptotic proteins that control cell survival by interrupting apoptosis and facilitating tumor development." (PMID 39598781, 2024). "Consistent with the in vitro experimental results, immunohistochemistry analysis showed that anti-JAM-A group had significantly lower expression of BCL-2 and IκBα than control group in nude mice tumor tissue, was related to the tumor volume of nude mice." (PMID 38495763, 2024). "Compared with the vector group, Ki67, BCL2, N-cadherin, and vimentin were upregulated, and Caspase3 and E-cadherin were downregulated in p65/S536A-overexpressing subcutaneous tumor tissues." (PMID 39498383, 2024). "A current report has revealed that normal expression of BAX in tumor cells was related with better consequences, while expression of BCL-2 in cancer cells affected drug resistance." (PMID 38287318, 2024). "RNA interference technologies such as siRNA and ASO can target oncogenes such as KRAS and BCL-2 to inhibit tumor growth and progression." (PMID 39857631, 2024). "Various senolytics, including ABT-263, interfere with the antiapoptotic proteins Bcl-2, Bcl-w, and Bcl-XL and have been investigated for their ability to eliminate senescent tumor cells that are induced by etoposide, doxorubicin, cisplatin, and radiation." (PMID 38567308, 2024). "Our findings demonstrated that NCAPD3 gene suppressed tumor cell apoptosis through up-regulation anti-apoptotic protein Bcl-2, while down-regulating pro-apoptotic proteins including caspase-8 and Bax, ultimately inactivating the apoptotic cascade in tumors." (PMID 38566039, 2024). "Tumor cells can gain apoptotic resistance by expressing anti-apoptotic proteins (e.g., Bcl-2) or inhibiting proapoptotic proteins (e.g., Bax)." (PMID 39123386, 2024). "Bcl-2, a key regulator of the mitochondrial pathway of apoptosis, is frequently overexpressed in various cancers, contributing to tumor growth, resistance to chemotherapy, and poor prognosis." (PMID 39407697, 2024). "In the tumor microenvironment, NF-κB upregulates the gene expression of anti-apoptotic proteins, such as Bcl-2 and Bcl-xL." (PMID 38572238, 2024). "Andro decreased Bcl-2 expression while increasing Bax protein expression in tumor tissues from treatment group mice." (PMID 38797813, 2024). "BCL2 is expressed in most DLBCL, NOS, and the cutoff level for BCL2 positivity is set to = or >50% of the tumor cells being BCL2 positive." (PMID 39684922, 2024). "A carrier, DPL, developed from diketopyrrolopyrrole (DPP), can facilitate targeted delivery of Bcl‐2 siRNA and enable tumor imaging both in vitro and in vivo." (PMID 39619229, 2024). "It has been suggested that this monoclonal antibody can inhibit the IL10-mediated loops and downregulate BCL-2 expression, leading to tumor drug resistance reversal." (PMID 38835350, 2024). "Bcl-2 is an antiapoptotic protein that can be upregulated in various cancers to promote tumor survival and prevent cell death, making Bcl-2 another possible target for treatment." (PMID 39456853, 2024).
tumor (continued). "The analysis of the expression of cell markers for tumor cells, for treatment only with Simvastatin, indicated a significant increase in the expression of Caspase 3 and Cytochrome c, and a decrease in Bcl2." (PMID 38255214, 2024). "In general, the combination induced extensive cell death within 24 h, suggesting that targeting AKT and BCL-2 has potential to enhance DLBCL tumour cell death." (PMID 39284898, 2024). "The antiapoptotic protein BCL-2 plays crucial roles in regulating oncogenesis, tumor survival, lymphocyte development and the immune response." (PMID 38062129, 2024). "By targeting and modifying the BCL-2 gene, researchers aim to disrupt the overexpression or dysregulation of this protein, which can lead to apoptosis resistance and tumor growth." (PMID 38195537, 2024). "Astragalosidei can induce the apoptosis of various tumor cells by decreasing the expression level of BCL-2 and increasing the expression level of BAX." (PMID 39323640, 2024). "Recent discoveries in the study of apoptosis and the tumor microenvironment have revealed that BCL-2 proteins are also important mediators of metabolic pathways." (PMID 38555418, 2024). "We demonstrated the Bcl-2-dependent modulation of Hippo Pathway in cancer cell lines from different tumor types by acting on upstream YAP regulators." (PMID 38755629, 2024). "Tan I (Tanshinone I) inhibited tumor growth by reversing the circ_0000376/miR-432-5p/Bcl-2 axis to trigger apoptosis in OS cells." (PMID 39524849, 2024). "For instance, in nasopharyngeal carcinoma and lung cancer, Curcumol has been observed to suppress tumor-promoting cytokines such as NF-κB, Bcl-2, and VEGF, while upregulating cytokines like PARP and AIF that promote apoptosis." (PMID 39170702, 2024). "Since tumor cells often inactivate the intrinsic mitochondrial apoptosis pathway (e.g., by overexpression of Bcl-2), these meriolin congeners represent promising therapeutic agents for overcoming therapeutic resistance." (PMID 39770138, 2024). "High levels of BCL-2 expression are frequently correlated with longer survival and a less aggressive tumor phenotype, especially in cases with positive hormone receptor status." (PMID 39685591, 2024). "MiR-15a-5p, as a suppressor of tumour formation, promotes apoptosis and inhibits tumour growth by targeting specific oncogenes, such as Bcl-2, CcnD1, Mcl1, and Wnt3A." (PMID 38698968, 2024). "This leads to increased expression of the pro-apoptotic protein BAX and inhibition of the anti-apoptotic protein Bcl-2, ultimately inducing tumor cell apoptosis." (PMID 38383702, 2024). "Bcl-2 also can inhibit the activity of caspase-9, 3, 6, and 7, thereby preventing apoptosis, leading to prolonged tumor cell survival and malignant cell transformation." (PMID 39126093, 2024). "Glabridin enhances tumor cell apoptosis by upregulating pro-apoptotic proteins Bax and Caspase-3 and downregulating anti-apoptotic proteins Bcl-2 and Procaspase-9." (PMID 39723390, 2024). "In healthy B cells, miR-15/16, a tandem of microRNAs, functions as a tumor suppressor, curbing the expression of the antiapoptotic B cell lymphoma 2 protein (Bcl-2)." (PMID 38543296, 2024). "BCL-2 integration enhances the anti-tumor activity of CAR-T cells in preclinical settings of mouse xenograft lymphoma, improving persistence and reducing RICD." (PMID 38891056, 2024). "The Bcl-2 protein acts as an oncogene by preventing tumor cells from undergoing apoptosis in response to radiation, chemotherapy, or hormonal therapy." (PMID 38167446, 2024). "Beyond that, western blot analysis exhibited that the protein levels of METTL14, AOC1, Cyclin D1, Bcl-2, and N-cadherin were clearly lower in tumor tissues derived from sh-METTL14-transfected C666-1 cells." (PMID 38956710, 2024).
tumor (continued). "Cell experiments revealed that T‐miR‐149 significantly enhanced the apoptosis‐promoting ability of free miR‐149 in tumour cells through the Pi3k/Akt and Akt/Bcl‐2 pathways, and in vivo experiments further confirmed the antitumor efficacy of T‐miR‐149." (PMID 38671577, 2024). "They revealed that nanophytosome encapsulated phenolic compounds notably developed the expression of bax and caspase genes and decrease the bcl2 gene in tumor cells." (PMID 38568336, 2024). "BCL2, a class of anti-apoptotic proteins, modulates apoptosis and promotes survival in tumor cells; While, the pro-apoptotic proteins BAX, and BAD, residing on the mitochondrial membrane is usually downregulated in tumor cells." (PMID 37025487, 2023). "Elevated protein levels of B-catenin, vimentin, and BCL2 have been evidenced to inhibit apoptosis and are frequently associated with epithelial mesenchymal transition (EMT) and tumor metastasis." (PMID 37542131, 2023). "This translocation involves the enhancer region of IGH partnering with the distal part of proto-oncogene BCL2, as well as subsequent anti-apoptosis of tumor cells." (PMID 36831263, 2023). "BCL-2 inhibitors represent a class of anti-tumor agents that are selective inhibitors of the anti-apoptotic protein B-cell lymphoma 2 (Bcl-2)." (PMID 37374055, 2023). "We observed that tumor heterogeneity contributes to variations in NP‐localization and sensitivity to combination BCL2/XLi and MCL1i inhibition." (PMID 36925689, 2023). "In particular, ccRCC cells have been found to express high levels of anti-apoptotic proteins, such as Bcl-2 and survivin, which hinder anoikis and sustain tumor cell survival." (PMID 37872217, 2023). "Biologically, induction of cancer with EAC cells resulted in a decrease in the gene expression of pro-apoptotic genes Bax and caspase-3 in tumor mass and a significant increase in anti-apoptotic gene Bcl-2 (EAC-treated group)." (PMID 37570713, 2023). "None of these agents, except SNS-032, significantly altered BCL-XL or BCL-2 levels in both tumor cells as well as normal cells." (PMID 36588105, 2023). "The rearrangement of the BCL2 gene endows cancer cells with anti-apoptotic ability, and Bcl-2 is considered a therapeutic target for tumor treatment." (PMID 36967521, 2023). "Bim is a widely recognized proapoptotic molecule of B-cell lymphoma 2 (Bcl-2) family, and acts as a crucial tumor suppressor gene taking part in the processes of apoptosis in a variety of cancers." (PMID 37928545, 2023). "Induction with EAC cells resulted in abnormalities in the gene expression of pro-apoptotic genes (Bax and caspase-3) and anti-apoptotic gene (Bcl-2) in the tumor mass." (PMID 37570713, 2023). "Hederagenin increases apoptosis by suppressing the anti-apoptotic protein Bcl-2 in tumor cells, and it primarily stimulates the mitochondrial endogenous apoptosis pathway by activating polyadenosine diphosphate ribose polymerase, caspase-3, caspase-9, and Bax." (PMID 37120556, 2023). "In particular, the activation of c-Jun augments MMP9 and Bcl-2 expressions, bolstering the tumor’s proliferation and metastatic potential." (PMID 38140058, 2023). "To evaluate the functional mechanism of exoLF on tumor cells, we measured the expression level of the Bid pro-apoptotic gene and Bcl-2 anti-apoptotic gene by Real-time PCR." (PMID 37422619, 2023). "At the concentration of 0.5 mM, Eug decreased the expression of the anti-apoptotic protein Bcl-2 and increased the expression of the pro-apoptotic proteins Bax and Bad in both tumor cell lines." (PMID 37896013, 2023).
tumor (continued). "The mRNA expression level of the BCL-2 gene was 1.5-fold increased in the tumor cells after cultivation with CIMVs-TRAIL in comparison with native MCF-7, native CIMVs and CIMVs-BFP (0.6-fold increase, both) (n = 3, **** p < 0.0001)." (PMID 36661524, 2023). "In vivo combination of trametinib with BCL-2 inhibitors led to tumor inhibition in NRAS-mutant and NF1-deleted xenografts." (PMID 36895472, 2023). "Further studies revealed that both miRNAs function as tumor suppressors that induce apoptosis by repressing an anti-apoptotic protein named B-cell lymphoma 2 (Bcl-2), which is overexpressed in hematological malignancies." (PMID 37104009, 2023). "Some aspects of tumor metabolism such as the overexpression of BCL1 and BCL2 play an important role not only in tumor initiation and progression but also in the development of resistance and the evasion of apoptosis." (PMID 37896202, 2023). "SeNPs are generally supposed to be able to trigger tumor cell apoptosis by increasing cellular uptake and cellular ROS levels via the expression of Bcl-2/Bax, and activation of caspase-3." (PMID 38188680, 2023). "BCL2 is widely known as a vital apoptosis suppressor that promotes tumor pathogenesis and DDP chemotherapy resistance by blocking mitochondrial apoptosis signaling pathways, including suppressing c-CASP3 and c-PARP." (PMID 36627670, 2023). "Forty percent of the tumor cells were positive for c-Myc, and 80% of tumor cells were positive for Bcl2." (PMID 37884941, 2023). "Ubiquitin-coupled enzyme 9 (ubc9), an essential E2-coupled enzyme of SUMOylation, has been found to prolong tumor cell survival through the function of B-cell lymphoma 2 (Bcl-2) in diverse cancers." (PMID 37777749, 2023). "The impact of abnormal over-expression of pro-survival BCL-2 proteins as well as abnormally reduced expression of pro-apoptotic BCL-2 family members on tumour development and the resistance of malignant cells to anti-cancer agents are well established." (PMID 36342579, 2023). "H&E staining showed that the xenograft tumors displayed typical characteristics of tumor cells, while the Ki-67- and Bcl-2-positive cells in the PTTG3P knockdown group were significantly lower than those in the control group." (PMID 37705754, 2023). "Overexpression of miR-15a-5p has been shown to inhibit cell growth and induce tumor cell apoptosis, primarily through the downregulation of Bcl-2 and Bcl-xl." (PMID 38140218, 2023). "We measured the levels of BAX and Bcl-2 in tumor tissues to further characterize the mechanism of the gut microbiota-related anti-CRC effects of our probiotic powder." (PMID 36913356, 2023). "As was known, the overexpression of apoptotic genes NF-kB and Bcl-2 were observed in tumor invasion and metastasis, which has been regarded as the potential target for cancer treatment." (PMID 36778126, 2023). "On the other hand, ARBs exert anti-tumor effects by increasing cancer cell autophagy through the induction of autophagy-related cell death and anti-metastatic activity, downregulating Bcl-2 and engaging in caspase-3-induced apoptosis pathways in cancer cells." (PMID 36836477, 2023). "In 100% of non-enhancing perifocal infiltrative edema zone tissue samples, we detected tumor cells with Ki-67 LI and Bcl-2 EA lower than in the contrast-enhancing tumor area." (PMID 37345097, 2023). "In tumor cells isolated from patients on the trial, we noted a significant decrease in Bcl-2:Bim or Mcl-1:Noxa complexes after 1 full cycle of treatment, suggesting increased availability of Bim to trigger mitochondrial-mediated programmed cell death." (PMID 36672426, 2023). "In pre-clinical studies, when tumor cells were pre-treated with Bcl-2 inhibitors, these cells were more easily killed by CAR-T cells, but studies associated with this result are limited." (PMID 36701037, 2023).